CACNA1F (calcium voltage-gated channel subunit alpha1 F)
Description:
[Isoform 1]: Voltage-sensitive calcium channels (VSCC) mediate the entry of calcium ions into excitable cells and are also involved in a variety of calcium-dependent processes, including muscle contraction, hormone or neurotransmitter release, gene expression, cell motility, cell division and cell death. The isoform alpha-1F gives rise to L-type calcium currents. Long-lasting (L-type) calcium channels belong to the 'high-voltage activated' (HVA) group. They are blocked by dihydropyridines (DHP), phenylalkylamines, and by benzothiazepines. Activates at more negative voltages and does not undergo calcium-dependent inactivation (CDI), due to incoming calcium ions, during depolarization. [Isoform 4]: Voltage-dependent L-type calcium channel activates at more hyperpolarized voltages and exhibits a robust calcium-dependent inactivation (CDI), due to incoming calcium ions, during depolarizations. [Isoform 5]: Voltage-sensitive calcium channels (VSCC) mediate the entry of calcium ions into excitable cells and are also involved in a variety of calcium-dependent processes, including muscle contraction, hormone or neurotransmitter release, gene expression, cell motility, cell division and cell death. [Isoform 6]: Voltage-dependent L-type calcium channel activates at more hyperpolarized voltages and exhibits a robust calcium-dependent inactivation (CDI), due to incoming calcium ions, during depolarizations.
Synonyms: Cav1.4; JM8; JMC8; CSNBX2; CORDX3; CSNB2A; OA2; AIED; COD3; COD4; CORDX; CSNB2; Cav1.4alpha1
Tractability: Small molecule: an approved drug acts on it; a high-quality ligand is known; it belongs to a druggable protein family. Antibody: UniProt predicts a signal peptide or a membrane-spanning region. PROTAC: a small molecule that binds it is known.
Gene: Protein-coding gene on chromosome X (49,205,063 to 49,233,371, reverse strand). Ensembl gene ENSG00000102001.
Subcellular location: Membrane
Gene Ontology:
Molecular function: voltage-gated calcium channel activity; high voltage-gated calcium channel activity; monoatomic ion channel activity
Biological process: detection of light stimulus involved in visual perception; visual perception; calcium ion import across plasma membrane; calcium ion transmembrane transport; monoatomic ion transport; transmembrane transport
Cellular component: membrane; voltage-gated calcium channel complex; neuronal cell body; perikaryon; photoreceptor outer segment
Gene-disease validity (ClinGen):
ClinGen rates the evidence that CACNA1F causes each of these diseases.
CACNA1F-related retinopathy (X-linked): Definitive. Any retinopathy caused by a variant in the CACNA1F gene.
Homologues: Orthologues: chimpanzee CACNA1F (99% identical), macaque CACNA1F (99% identical), pig CACNA1F (94% identical), dog CACNA1F (94% identical), mouse Cacna1f (92% identical), rat Cacna1f (92% identical), guinea pig CACNA1F (82% identical), rabbit CACNA1F (81% identical), zebrafish cacna1fb (70% identical), tropical clawed frog cacna1f (70% identical). Paralogues in human: CACNA1D (68% identical), CACNA1C (62% identical), CACNA1S (56% identical), CACNA1B (40% identical), CACNA1A (39% identical), CACNA1E (38% identical), CACNA1H (25% identical), CACNA1I (25% identical), CACNA1G (24% identical), SCN2A (24% identical), SCN3A (23% identical), SCN9A (23% identical), and 14 more.
Diseases named in the same sentence as CACNA1F in open-access papers:
CACNA1F is named in the same sentence as 76 diseases in open-access papers, as found by Europe PMC text mining. Sharing a sentence is not in itself a finding about the gene and the disease. The quoted sentences say what the papers report.
congenital stationary night blindness (22 papers, 2007 to 2025). "As for the CACNA1F gene mutation, it is related to X-linked retinal disorders, such as congenital stationary night blindness, cone-rod dystrophy, and Åland Island eye disease, all connected with a calcium channel dysfunction in retinal photoreceptor synapses." (PMID 41303269, 2025). "Causal alterations in the CACNA1F gene are responsible for incomplete congenital stationary night blindness 2A (OMIM #300071) and retinal dystrophy (OMIM #300476)." (PMID 39495751, 2024). "CACNA1F is the first gene found on the X chromosome to cause congenital stationary night blindness (CSNB)." (PMID 38028590, 2023). "Hemizygous pathogenic variants in CACNA1F lead to defective signal transmission from retinal photoreceptors to bipolar cells and cause incomplete congenital stationary night blindness in humans." (PMID 33668843, 2021). "The original discovery of CaV1.4 is intimately associated with the phenotypic and genotypic characterization of a family of inherited retinal disorders, congenital stationary night blindness (CSNB), a subset of which (CSNB2A) is caused by mutations in CACNA1F." (PMID 29854783, 2018). "Likely gain-of-function mutations in CACNA1F cause congenital stationary night blindness in both sexes." (PMID 29449410, 2018). "Mutations in the CACNA1F gene encoding the L-type calcium channel pore-forming Cav1.4 (α1F) subunit in humans result in an incomplete form of congenital stationary night blindness (CSNB2) with residual photoreceptor function." (PMID 17563731, 2007). "Clinical details and properties of the 10 novel CACNA1F variants of unknown significance (VUS) identified at the Manchester Genomics Diagnostic Laboratory in patients with congenital stationary night blindness (CSNB)." (PMID 37206923, 2023). "In addition to RDS and RPGR, the CACNA1F gene, whose mutations lead to X-linked congenital stationary night blindness, is mutated in one CRD Finnish family previously mapped as CORDX3 (or COD4)." (PMID 17270046, 2007). "These systemic syndromes can be caused by a series of genes, including NYX, CACNA1F, GRM6, and LRIT3, responsible for congenital stationary night blindness (CSNB); COL2A1, COL11A1, COL9A1, and COL9A2, responsible for Stickler syndrome; and FBN1, responsible for Marfan syndrome." (PMID 36980859, 2023). "Congenital stationary night blindness 2A (CSNB2A) is a genetic retinal disorder characterized by poor visual acuity, nystagmus, strabismus, and other signs of retinal dysfunction resulting from mutations in Cacna1f—the gene coding for the pore-forming subunit of the calcium channel CaV1.4." (PMID 33117610, 2020).
Cone rod dystrophy (16 papers, 2013 to 2025). "Another gene associated with the same phenotype of CSNB is CACNA1F, a gene present in the X chromosome and related to Aland Island disease and cone-rod dystrophy." (PMID 35457050, 2022). "Some people with CACNA1F mutations have been diagnosed with cone-rod dystrophy." (PMID 37181655, 2023). "However, a few CACNA1F mutations have been associated with variant progressive disorders, e.g. a splice site mutation in a family with cone-rod dystrophy, and an in-frame deletion and insertion in two brothers with retinal and optic disc atrophy." (PMID 24466230, 2014). "This case highlights the phenotypic heterogeneity of CACNA1F-related disorders and suggests rod-cone dystrophy as a potential additional phenotype." (PMID 40390739, 2025). "Three significant phenotypes associated with mutations in the CACNA1F gene have been well-described: congenital stationary night blindness type 2A (CSNB2A), cone-rod dystrophy (CORDX3), and Åland Island eye disease (AIED)." (PMID 40390739, 2025). "Mutations in the gene of Cav1.4, CACNA1F, can lead to X-linked retinal diseases such as Åland Island Eye Disease (AIED), cone-rod dystrophy (CORDX3) or congenital stationary night blindness type 2 (CSNB2)." (PMID 36943941, 2023). "Mutation in CACNA1F has been reported to be associated with X-linked congenital stationary night blindness (CSNB), Cone-rod dystrophy-3 (CORDX3), and Aland Island eye disease (AIED)." (PMID 26075273, 2015). "Mutations in the CACNA1F gene are associated with various X-linked retinal disorders, including congenital stationary night blindness type 2A (CSNB2A), cone-rod dystrophy (CORDX3), and Åland Island eye disease (AIED), due to their role in calcium channel function in retinal photoreceptor synapses." (PMID 40390739, 2025). "In addition to CSNB2, CACNA1F mutations are also known to cause X-linked Cone-Rod Dystrophy 3 (CORDX3), Åland Eye Disease, and even a progressive retinal/optic disc atrophy." (PMID 29854783, 2018). "Due to the heterogeneity of cone-rod dystrophies, we performed a combined linkage and X-exome sequencing approach and identified a novel large intragenic in-frame deletion encompassing exons 18 to 26 within the CACNA1F gene." (PMID 24124559, 2013). "This case contributes to the phenotypic spectrum associated with CACNA1F mutations by presenting the case of a 33-year-old male patient with clinical and functional findings consistent with rod-cone dystrophy, a phenotype not classically associated with this gene." (PMID 40390739, 2025). "It is worth noting though that, despite the fact that a number of different ophthalmic conditions has been linked to CACNA1F variants (including iCSNB, Åland eye disease and X-linked cone-rod dystrophy 3), incomplete penetrance is certainly not a frequent feature of CACNA1F-related disorders." (PMID 32313206, 2020).
Aland island eye disease (15 papers, 2008 to 2025). An X-linked recessive retinal disease characterized by fundus hypopigmentation, decrased visual acuity, nystagmus, astigmatism, progressive axial myopia, defective dark adaptation and protanopia. "Other conditions such as Aland Island Eye disease caused by a mutation in CACNA1F and Waardenburg Syndrome associated with PAX3 mutations can have similar clinical findings of albinism on ocular exam." (PMID 36672876, 2023). "CACNA1F variations have additionally been identified in large families diagnosed with Åland Island Eye Disease (AED) or X-linked Cone-Rod Dystrophy type 3 (CORDX3)." (PMID 30186847, 2018). "Additionally, some studies found that CACNA1F is closely associated with the onset of Aland Island eye disease, characterized by fundus pigmentation, reduced visual acuity, nystagmus, astigmatism, color vision defects, and dark maladjustment." (PMID 38028590, 2023). "However, a few CACNA1F alterations have been associated with CSNB2-related but distinctive phenotypes such as Åland Island eye disease (ÅIED), X-linked cone-rod dystrophy (CORDX3), or a retinal disorder associated with intellectual disability, respectively." (PMID 24124559, 2013). "An intronic-exonic deletion of 425bp encompassing exon 30 and adjacent introns of CACNA1F resulted in the deletion of the TM domain and extracellular loop of Cav1.4α1 in a patient with Aland Island eye disease (AIED), a nearly identical disorder to CSNB2." (PMID 32967234, 2020). "Hemizygous pathogenic mutations in CACNA1F cause X-linked disorders including incomplete congenital stationary night blindness type 2 (CSNB2), cone-rod dystrophy (CORDX3) and Aland Island eye disease (AIED)." (PMID 41153400, 2025).
congenital stationary night blindness type 2 (15 papers, 2011 to 2025). "Pathogenic variants in the CACNA1F gene are linked to congenital stationary night blindness type 2 though their specific molecular effects remain elusive." (PMID 41224078, 2025). "More than 200 mutations in CACNA1F cause vision disorders including congenital stationary night blindness type 2 (CSNB2)." (PMID 39531384, 2024). "Pathogenic, generally loss-of-function, variants in CACNA1F, encoding the Cav1.4α1 calcium channel, underlie congenital stationary night blindness type 2 (CSNB2), a rare inherited retinal disorder associated with visual disability." (PMID 37206923, 2023). "Patient 6 carries a heterozygous variant in the CACNA1F gene, which causes X-linked incomplete CSNB (iCSNB)." (PMID 36499293, 2022). "In humans, mutations in the CACNA1F gene encoding for Cav1.4 channels are associated with X-linked retinal disorders such as congenital stationary night blindness type 2." (PMID 34212239, 2021). "Pathogenic variants in the CACNA1f gene cause congenital stationary night blindness type 2, yet their molecular effects remain unclear." (PMID 41224078, 2025). "Mutations in its gene, CACNA1F, can cause congenital stationary night-blindness type 2 (CSNB2)." (PMID 36943941, 2023). "Mutations in the α1 subunit of the L-type voltage gated Ca2+ channel gene (CACNA1F; OMIM *300110) is associated with X-linked incomplete CSNB (CSNB2A; OMIM #300071)." (PMID 22194652, 2011).
myopia (13 papers, 2011 to 2026). "Our results align with previous studies, such as Hendriks and associates’ findings on CSNB patients, who demonstrated high myopia, especially in those with mutations in the CACNA1F, NYX, and TRPM1 genes." (PMID 40935931, 2025). "The more commonly associated gene with iCSNB is the X-linked CACNA1F, but variants in this gene cause disease in males, usually with high myopia (whilst our patient was female and hypermetropic)." (PMID 38206458, 2024). "Humans with congenital loss of ON-pathway signals (complete CSNB) are usually highly myopic, although myopia is also a typical feature of CACNA1F-associated incomplete CSNB, in which there is attenuation of both ON and OFF pathways." (PMID 39530998, 2024). "In humans with congenital ON-pathway loss (complete CSNB), high myopia is usually seen; however, CACNA1F-associated disease (sometimes termed “incomplete” CSNB), which entails attenuation of both ON- and OFF-pathway signals, is also associated with myopia." (PMID 35594404, 2022). "Importantly, all CACNA1F-related phenotypes are associated with high myopia." (PMID 41153400, 2025). "Igelman and associates focused on the progressive aspect of myopia among CSNB paediatric patients, analysing samples of 78 paediatric patients with CSNB, out of which 41 with CACNA1F, 22 with NYX and 15 with TRPM1 genes." (PMID 40935931, 2025). "One study examined 50 patients with high myopia, and genetic testing determined that 4 of the patients had mutations linked with retinal dystrophies (GUCY2D, FAM161A, PDE6H, CACNA1F), suggesting an association between GUCY2D and high myopia." (PMID 41153400, 2025). "Further, we showed that inner retinal thinning in CACNA1F-related iCSNB patients is in excess of controls with the same degree of myopia, strongly suggesting the possibility that optic pallor is consistent with optic atrophy, which is likely overlooked in CACNA1F-related iCSNB as a whole." (PMID 33668843, 2021).
Nystagmus (13 papers, 2011 to 2025). Rhythmic, involuntary oscillations of one or both eyes related to abnormality in fixation, conjugate gaze, or vestibular mechanisms. "Among the 14 patients with CACNA1F mutations, 10 (71%) had nystagmus." (PMID 34064005, 2021). "Notably, MST465-II:1 exhibits nystagmus, a common feature in CACNA1F-associated disease." (PMID 40269797, 2025). "The incidence of nystagmus (50%), nyctalopia (50%) and photophobia (44%) in our cohort was similar to those identified in two large studies of CACNA1F-related iCSNB, which documented rates of 44–65%, 58–60% and 50%, respectively." (PMID 33668843, 2021). "Hemizygous missense (c.299T>G, p.(Leu100Arg)) and nonsense (c.2905C>T, p.(Arg969Ter)) variants of CACNA1F were identified in NYS-002 and NYS-004, respectively; both patients were male subjects with reduced visual acuity and predominantly horizontal nystagmus with a vertical component." (PMID 28378818, 2017).
night blindness (10 papers, 2010 to 2025). Inability to see clearly in dim light. "A variation in CACNA1F gene encoding for CaV1.4 of Ca2+ channel was detected in a family with inherited night blindness and ASD." (PMID 29934975, 2018). "Given the phenotypic variability within iCSNB and the fact that many patients complain of photophobia, rather than nyctalopia, “congenital rod-cone synaptic disorder” is a recently proposed term for the CACNA1F-related disorder." (PMID 33668843, 2021).
retinal diseases (10 papers, 2019 to 2025). "A multimodal diagnostic approach is recommended when evaluating patients with inherited retinal diseases, especially those with CACNA1F mutations." (PMID 40390739, 2025). "The mutations in the CACNA1F gene that encodes Cav1.4 channels lead to the the channel activity altered and caused the retinal disease, for example, CSNB2." (PMID 38773596, 2024). "The CNGA3, CACNA1F, and RPGRIP1 genes are the most well-known from our list, and this article discusses their photoreceptor function and implications in retinal diseases." (PMID 40737315, 2025).
achromatopsia (7 papers, 2020 to 2025). Achromatopsia (ACHM) is a rare autosomal recessive retinal disorder characterized by color blindness, nystagmus, photophobia, and severely reduced visual acuity due to the absence or impairment of cone function. "Here, pathogenic variants in CNGB3 were the most common cause of achromatopsia (ACHM), and variants in CACNA1F were the most prevalent cause of CSNB." (PMID 33749171, 2021).
retinal dystrophies (7 papers, 2019 to 2025). "Among cases of high myopia with ocular involvement (38.9%), a genetic cause was found in 8 out of 14 probands, including (likely) pathogenic variants in genes related to retinal dystrophies (CACNA1F, RPGR, RP2, NDP)." (PMID 39495751, 2024). "Our case contributes valuable clinical correlation to this variant, further defining its role within the phenotypic spectrum of CACNA1F-related retinal dystrophies." (PMID 40390739, 2025). "In the group with only ocular involvement, we observed 6 cases of (probably) pathogenic variants in genes associated with retinal dystrophies (RPGR; N = 2, CACNA1F; N = 2, RP2, NDP), which corresponds to 27.3% of all genetically confirmed cases of HM." (PMID 39495751, 2024). "Furthermore, 24 families had VUS, two families with variants in genes related to non-syndromic EoHM (SCO2 and ZNF644) and seven families with variants in genes associated with other retinal dystrophies (TRPM1, CACNA1F, KCNV2, RDH5 and MERTK)." (PMID 35457050, 2022). "Specifically, HM was identified in six children with retinal dystrophies (RPGR; N = 2, CACNA1F; N = 2, RP2, NDP) and one child each of corneal dystrophy (ZEB1) and Stickler syndrome (causative variant in the COL9A2 gene)." (PMID 39495751, 2024).
retinal degeneration (5 papers, 2016 to 2024). Degeneration of the retina. "Specifically, Cacna1f-knockout mice show an apparent lack of visual function, gradual retinal degeneration, and disruption of photoreceptor synaptic terminals." (PMID 29179637, 2018). "Longitudinal in vivo examinations of photoreceptor layer thickness by optical coherence tomography revealed a significant, but not sustained delay of retinal degeneration in Cacna1f x rd1 double mutant mice compared to rd1 mice." (PMID 27270916, 2016).
optic atrophy (4 papers, 2014 to 2024). A disorder characterized by loss of optic nerve fibers. "A retrospective study in 22 males with molecularly confirmed hemizygous mutations in CACNA1F establishes macular inner retinal thinning and optic atrophy as characteristic features of CACNA1F-retinopathy." (PMID 39564550, 2024). "Additional cases must be gathered to understand the genotype–phenotype correlation in CACNA1F associated with optic atrophy." (PMID 39564550, 2024).
X-linked congenital stationary night blindness (4 papers, 2008 to 2015). X-linked congenital stationary night blindness (XLCSNB) is a disorder of the retina. "Mutations in NYX and CACNA1F gene are responsible for the X-linked congenital stationary night blindness (CSNB)." (PMID 26234941, 2015). "NYX and CACNA1F genes are two disease-causing genes for X-linked congenital stationary night blindness." (PMID 26234941, 2015). "Mutations in the human CACNA1F gene encoding the α1F subunit of Cav1.4 channels cause an incomplete form of X-linked congenital stationary night blindness (CSNB2)." (PMID 24466230, 2014). "The Cacna1f mutation identified in the rat model of CSNB was predicted to lead to a protein product that is shortened by 999 amino acids, indicating that this is a model for the incomplete subtype of human X-linked CSNB (CSNB2)." (PMID 18246026, 2008).